AFG1L (AFG1 like ATPase)
Description:
Putative mitochondrial ATPase. Plays a role in mitochondrial morphology and mitochondrial protein metabolism. Promotes degradation of excess nuclear-encoded complex IV subunits (COX4I1, COX5A and COX6A1) and normal activity of complexes III and IV of the respiratory chain.
Synonyms: AFG1; LACE1; c222389
Tractability: No criterion of Open Targets' tractability assessment is met for any kind of drug.
Gene: Protein-coding gene on chromosome 6 (108,294,926 to 108,526,796, forward strand). Ensembl gene ENSG00000135537.
Subcellular location: Mitochondrion membrane
Gene Ontology:
Molecular function: protein binding; ATP hydrolysis activity; ATP binding
Biological process: mitochondrial protein catabolic process; mitochondrial protein quality control; mitochondrion organization
Cellular component: mitochondrial membrane; mitochondrion; cytoplasm
Genetic constraint (gnomAD): Loss-of-function variants: 18 observed, 26.21 expected, observed/expected ratio (o/e) 0.69, 90% interval 0.47 to 1.02. The upper end of that interval is the gene's LOEUF score, 1.02, which puts it in group 4 of 6, group 1 being the genes least tolerant of losing a copy. Missense variants: 303 observed, 324.43 expected, observed/expected ratio (o/e) 0.93, 90% interval 0.85 to 1.03. Synonymous variants: 146 observed, 129.44 expected, observed/expected ratio (o/e) 1.13, 90% interval 0.99 to 1.29.
Homologues: Orthologues: chimpanzee AFG1L (100% identical), macaque AFG1L (98% identical), pig AFG1L (93% identical), dog AFG1L (91% identical), mouse Afg1l (87% identical), rat AABR07045431.1 (86% identical), guinea pig AFG1L (83% identical), rabbit AFG1L (82% identical), tropical clawed frog afg1l (69% identical), zebrafish afg1la (60% identical), Drosophila melanogaster CG8520 (40% identical), Caenorhabditis elegans C30F12.2 (37% identical).
Diseases named in the same sentence as AFG1L in open-access papers:
AFG1L is named in the same sentence as 14 diseases in open-access papers, as found by Europe PMC text mining. Sharing a sentence is not in itself a finding about the gene and the disease.
AFG1L shares sentences with these, for which no sentence is quoted: tumor (4 papers); hepatocellular carcinoma (2); lung carcinoma (2); adenocarcinoma (1); bipolar disorder (1); cancer (1); dementia (1); esophageal cancer (1); infection (1); kidney tumors (1); liver cancer (1); lung adenocarcinoma (1); neurodegenerative disease (1); Obesity (1).